METTL3 (methyltransferase 3, N6-adenosine-methyltransferase complex catalytic subunit)
Diseases named in the same sentence as METTL3 in open-access papers (continued):
Sharing a sentence is not in itself a finding about the gene and the disease.
tumor (continued). "In HCC, METTL3 promotes tumor growth by regulating oncogenic and tumor-suppressing genes, including SNAIL, YAP1, LINC00958, and SOCS2." (PMID 40302799, 2025). "METTL3’s role is context-specific, functioning as either an oncogenic driver or a tumor-suppressive factor depending on the cellular environment." (PMID 41515964, 2025). "96In summary, these findings demonstrate that METTL3 plays an essential role in promoting the occurrence and development of tumors by enhancing the synthesis of tumor-promoting factor miRNAs in various cancers." (PMID 40734692, 2025). "Our findings suggest that METTL3 and m6A modification play a tumor‐suppressive role in the early stages of HCC, challenging the existing paradigm of its function based on studies in established cancer models." (PMID 40103332, 2025). "Tumor MO-MDSC also showed higher Mettl3 levels than wild-type CD11b+Ly6C+ cells, with pMΦ exhibiting the lowest levels." (PMID 41360769, 2025). "Accumulated lactate in the tumor microenvironment effectively induces the upregulation of METTL3 in tumor-infiltrating myeloid cells (TIMs) through H3K18la, and Kla modification on the zinc-finger region of METTL3 boosts its ability to bind m6A-modified RNA." (PMID 40563450, 2025). "After 24 h of ATRA exposure, Mettl3 in tumor MO-MDSC decreased, similar to the changes seen in ATRA-induced MΦ compared to the original MO-MDSC." (PMID 41360769, 2025). "METTL3 inhibition or knockout affects tumor cell proliferation and tumor growth, with YTHDF2 playing a key role and enhancing antitumor effects in a T-cell-dependent manner, indicating that YTHDF2 is a downstream executor of STM2457’s antitumor effects." (PMID 40678060, 2025). "In BCa, METTL3 exhibits multifaceted oncogenic roles, significantly influencing patient prognosis by promoting tumor cell proliferation, migration, invasion, and chemoresistance." (PMID 40678060, 2025). "In mouse models, siRNA-mediated silencing of the METTL3 gene significantly inhibits BCa tumor growth and metastasis." (PMID 40678060, 2025). "For example, analyzing how m6A modification mediated by METTL3 in local neuronal synapses regulates synaptic plasticity, or the “cross-talk” between immune cells and cancer cells in the tumor microenvironment by METTL1." (PMID 41194259, 2025). "METTL3 overexpression has been correlated with poor prognosis, increased tumor grade, and reduced survival in HCC patients." (PMID 41011154, 2025). "For instance, the lactylation of METTL3 is critical for its ability to capture target RNA, thereby promoting the immunosuppression of tumor-infiltrating myeloid cells." (PMID 39849461, 2025). "Lactate in tumor-infiltrating myeloid cells upregulates METTL3 expression, and METTL3 lactylation is essential for capturing target RNA and maintaining the immunosuppressive capacity of tumor-infiltrating myeloid cells." (PMID 40651967, 2025). "Early studies have shown that aberrant METTL3 expression levels correlate with clinical features such as tumor stage, metastasis, and overall survival rates in CRC patients." (PMID 40177651, 2025). "Second, writer effects diverge: METTL3 can promote antigen presentation via NLRC5 in tumor cells but is also required for DC co-stimulation—raising the practical challenge of cell-type–selective delivery or reader-focused strategies." (PMID 41280938, 2025). "METTL3 promotes tumor proliferation and PD-L1-mediated immune escape while METTL14 can inhibit tumorigenesis in the bladder." (PMID 40133252, 2025). "Depletion of METTL3 in TAMs enhances both M1 and M2-like TAMs, as well as Treg infiltration into tumors, remodeling the tumor microenvironment and promoting tumor growth and metastasis." (PMID 39897038, 2025). "Knockdown of METTL3 significantly suppresses tumor development in vivo and inhibits NSCLC cell migration and invasion." (PMID 40271153, 2025). "These trials focus on evaluating the safety, pharmacokinetics, and anti-tumor efficacy of METTL3 inhibitors." (PMID 41515964, 2025).
tumor (continued). "H3K18la promotes the immune suppression effect of tumor-infiltrating myeloid cells by promoting the expression of METTL3." (PMID 41199784, 2025). "This study not only elucidates the biological function of lactylated METTL3 in tumor cells but also highlights its negative regulatory effect on cisplatin resistance." (PMID 39950833, 2025). "In vivo, tumor formation experiments demonstrated that EIF3J-AS1 inhibition in METTL3-overexpressing cells significantly suppressed tumor growth." (PMID 41390674, 2025). "For instance, conventional high‐grade OS, which is the most prevalent form, often exhibits significant METTL3 overexpression, correlating with aggressive tumour features and poor prognosis." (PMID 40052548, 2025). "Related studies have also suggested that nuclear METTL3 and cytoplasmic METTL3 have distinct functions in driving tumorigenesis and how tumor cells sense carcinogenic damage to coordinate the functions of METTL3 in these intracellular compartments." (PMID 41321637, 2025). "This lactylation not only prevents RBM15 protein degradation but also enhances its interaction with the m6A methyltransferase METTL3, thereby elevating global m6A levels and further driving tumor cell proliferation and migration." (PMID 41403702, 2025). "It has been discovered that METTL3 targets the tumour suppressor SOCS2, and that this is accomplished by epigenetic m6A alteration." (PMID 41011154, 2025). "Research indicates that METTL3 facilitates tumor progression by regulating genes such as Bcl-2, EPPK1, and ACIN1." (PMID 40572597, 2025). "Studies have shown that the accumulation of lactate in the tumor microenvironment can induce the upregulation of METTL3 in tumor-infiltrating immune cells through H3K18 lactylation, a process crucial for METTL3 to bind to target RNA." (PMID 40136363, 2025). "We found that mRNA and protein levels of METTL3 were highly expressed in tumor cells compared with healthy donors." (PMID 40332203, 2025). "Studies have demonstrated that METTL3 enhances tumor cell proliferation and invasion through the MYC, inhibitor of nuclear factor kappa-B kinase subunit beta (IKBKB), and RELA proto-oncogene, NF-kB subunit (RELA) signaling pathways." (PMID 40678060, 2025). "In CC, the RNA methyltransferase METTL3 is frequently overexpressed and accelerates the degradation of target mRNAs through m6A modification, thereby remodeling tumor-related transcriptional networks." (PMID 41256331, 2025). "We also identified the high expression of METTL3 in EC tissues and cells and its promoting effects on EC cell proliferation, migration and invasion as well as tumor formation." (PMID 39980152, 2025). "In tumor-associated macrophages (TAM), METTL3 can induce the M1 antitumor state of macrophages by increasing the compactness of STAT1 mRNA." (PMID 40565233, 2025). "For example, the m6A writer METTL3 exhibits both oncogenic and tumor-suppressive abilities in the same cancer type." (PMID 41285728, 2025). "The E3 ligase TRIM21 mediated K48-linked polyubiquitination of METTL3 at the K459 site, leading to the proteasomal degradation of METTL3, which prevented tumor progression by promoting ferroptosis." (PMID 40175350, 2025). "Research has elucidated that METTL3 is anomalously overexpressed in ccRCC and is instrumental in driving tumor metastasis, metabolic reprogramming, and resistance to anticancer therapies." (PMID 40313614, 2025). "Rescue experiments further demonstrated that silencing STEAP2 reverses the tumor-suppressive effects induced by METTL3 overexpression, highlighting the METTL3-STEAP2 axis as a therapeutic target in PTC." (PMID 40463874, 2025). "For example, overexpression of the methyltransferase METTL3 has been shown to increase the stability of oncogenes and promote tumor growth, whereas the demethylase FTO induces m6A demethylation to increase the expression of multidrug resistance genes." (PMID 40356985, 2025).
tumor (continued). "Studies have demonstrated that METTL3 precisely regulates the expression of tumor-related genes by modulating the levels of m6A modification." (PMID 40678060, 2025). "Treatment with STM2457, a selective catalytic inhibitor of METTL3, reduces tumor growth while promoting differentiation and apoptosis in AML." (PMID 40271153, 2025). "To date, a small molecule inhibitor targeting METTL3 has been documented to exhibit remarkable anti‐tumor efficacy, particularly in AML." (PMID 40171845, 2025). "The results demonstrated that EEF2, G3BP1, G3BP2, PRPF8, RECQL4, STOML2, and UBB exhibited significantly higher expression levels in the majority of tumor tissues, whereas METTL3 and NR2C2 showed a widespread downregulation trend." (PMID 41341921, 2025). "Overall, these findings highlight the importance of Mettl3-mediated m6A modification at the 3’UTR of Smad3 mRNA in its low expression in tumor MO-MDSC, due to impaired mRNA stability by Ythdf2 recognition." (PMID 41360769, 2025). "Beyond its role in mRNA modification, METTL3 also targets lncRNAs that are crucial for tumorigenesis and cancer progression, thus positioning them as innovative tumor markers." (PMID 40313614, 2025). "In PDAC, neuronal glutamate release activates NMDAR on tumor cells, triggering calcium influx and promoting the transcription of methyltransferase-like 3 (METTL3)." (PMID 41163091, 2025). "METTL3 has been shown to facilitate tumor progression by recruiting TAMs and inhibiting M1 macrophage polarization." (PMID 41316520, 2025). "Taken together, we report that METTL3, an oncogene regulates the expression of SMAD4, a tumor-suppressor via miR-146a-5p, thus unveiling a novel regulatory axis of METTL3/miR-146a-5p/SMAD4 in OSCC, which can potentially have therapeutic implications." (PMID 40338154, 2025). "While METTL3 appears to act as a tumor suppressor in a few cancers, many reports suggest that METTL3 functions as an oncogene in numerous cancer types." (PMID 41245600, 2025). "Psychological stress stabilizes FSP1 mRNA through the METTL3-mediated m6A modification, suppressing ferroptosis and promoting tumor progression." (PMID 40862825, 2025). "Our research, along with that of others, suggests that dysregulated PTM of METTL3 significantly contributes to tumor initiation and progression." (PMID 40651967, 2025). "Circ_0001187 regulates AML progression through the miR-499a-5p/RNF113A/METTL3 axis and acts as a key tumor suppressor in AML." (PMID 41229443, 2025). "We observed that METTL3 expression was downregulated in ICCA, and this reduction was significantly associated with enhanced tumor proliferation and migration." (PMID 41208889, 2025). "This review synthesizes current evidence on METTL3’s functions, revealing its oncogenic activity through m6A-mediated regulation of RNA stability and translation, which promotes tumor progression, metastasis, and chemoresistance." (PMID 40313614, 2025). "Contrary to previous findings in established HCC, in our research, METTL3 was identified as a tumor suppressor during the early stage of HCC occurrence." (PMID 40103332, 2025). "Acetylation of METTL3 at K177 inhibits m6A modification and suppresses tumor metastasis by attenuating its translocation from the cytoplasm to the nucleus." (PMID 41321637, 2025). "In vitro, the hydrogel promoted CAR-NK cell recruitment and tumor killing via sustained METTL3 inhibition." (PMID 39497707, 2025). "Regarding the regulation of SLC7A11, METTL3 promotes lung adenocarcinoma (LUAD) tumor growth and inhibits ferroptosis by stabilizing the m6A modification of SLC7A11." (PMID 39800682, 2025). "We designed an adhesive hemostasis hydrogel loaded with STM2457, a METTL3 inhibitor, aimed at sustained release in the acidic tumor microenvironment." (PMID 39497707, 2025). "High METTL3 expression in cancer significantly increases glucose uptake and lactate production, enhances glycolysis, and promotes tumor growth." (PMID 40046061, 2025).
tumor (continued). "An earlier study revealed that elevated METTL3 levels in CC tissues were positively correlated with the presence of CD33+ cells within the tumour and with the clinical outcomes of patients." (PMID 40356909, 2025). "To further explore the clinical applicability of targeting METTL3 in HCC therapy, we investigated the impact of the METTL3 inhibitor, STM2457, on the susceptibility of HCC to OXA in orthotopic tumor models." (PMID 39472692, 2025). "High METTL3 activity enhances m6A modifications on tumor suppressor transcripts, leading to their degradation via YTHDF2, thereby supporting oncogenic progression." (PMID 41011154, 2025). "More and more studies have found that METTL3 shows a significant upward trend in BCa tumor tissues, and the overexpression of METTL3 significantly promotes the growth and invasion of BCa cells." (PMID 40678060, 2025). "Numerous studies have underscored the oncogenic function of METTL3 in human ccRCC, emphasizing its crucial role in tumor progression and prognostic evaluation." (PMID 40313614, 2025). "Clinically, METTL3 overexpression correlates with advanced tumor stage, poor prognosis, and resistance to TKIs, solidifying its dual utility as a diagnostic/prognostic biomarker and a therapeutic target." (PMID 40313614, 2025). "For instance, the role of METTL3 in stabilizing oncogenic transcripts such as HDGF and long non-coding RNAs (e.g., PSMA3-AS1, MIR22HG) is strongly linked to GCSC self-renewal and tumor initiation capacity." (PMID 41228380, 2025). "STC-15, the first METTL3 inhibitor to undergo a clinical evaluation, has been shown to have the potential to inhibit tumor growth through immune mechanisms." (PMID 40747121, 2025). "In summary, while the current literature elucidates the significant role of METTL3 in OS progression, a more nuanced understanding of its function across different tumour subtypes and its interactions within the tumour microenvironment is essential." (PMID 40052548, 2025). "CircPUM1, for example, promotes METTL3 expression via sponge miR-590-5p and has an impact on tumor cell proliferation and glycolytic processes." (PMID 39904996, 2025). "METTL3 is frequently upregulated and promotes tumor initiation, proliferation, and metastasis through the AKT and EGR1/Snail pathways, while also enhancing glutamine metabolism." (PMID 41228380, 2025). "In patients with CRC, the expression of the METTL3 protein exhibited a significant correlation with the infiltration of CD33 + MDSCs in tumor tissues." (PMID 39987091, 2025). "Histone lactylation drives METTL3-mediated RNA m6A modifications, which are pivotal in enhancing the immunosuppressive capacity of tumor-infiltrating myeloid cells (TIMs)." (PMID 40806283, 2025). "It was discovered in a tumor-based study that METTL3 and METTL14 act on miR-380-3p through a m6A modification-dependent mechanism." (PMID 39904996, 2025). "Tumor-infiltrating MDSCs show markedly increased levels of methyltransferase-like 3 (METTL3), which enhances their immunosuppressive function via the m6A/JAK1/STAT3 signaling axis." (PMID 41152975, 2025). "For example, exposure to arsenic suppresses METTL3, an m6A “writer,” reducing methylation of tumor suppressor transcripts and promoting carcinogenesis." (PMID 40760453, 2025). "High METTL3 expression correlates with advanced tumor stage, poor prognosis, and resistance to TKIs in ccRCC, positioning it as a predictive biomarker." (PMID 40313614, 2025). "This immune suppression facilitated by METTL3 impairs the tumor’s ability to be targeted by the immune system, contributing to its progression and resistance to immune therapies." (PMID 39911396, 2025). "Previous studies examining the functions of METTL3 and METTL14 in BCa have reported both tumour suppressor and oncogenic roles and have implicated METTL3 and METTL14 in several mechanisms." (PMID 41310336, 2025).
tumor (continued). "Lactylation can also occur directly on the CCCH‐type zinc finger domain of human METTL3 protein, mediating tumor immune evasion." (PMID 40443721, 2025). "This database shows frequently anomalous expressions of these enzymes, and METTL3 expression is always notably elevated in these tumor types." (PMID 40136363, 2025). "RSM3, a stapled peptide inhibitor, not only inhibits Mettl3's catalytic activity but also induces its degradation via the proteasome pathway, showing anti-cancer effects in multiple tumor models." (PMID 40765834, 2025). "CircMVP mediated CTNNB1 m6A modification by promoting METTL3 activation and inhibited B7-H3-dependent anti-tumor immune response in CRC." (PMID 39744434, 2025). "Methyltransferase-like 3 (METTL3), a key RNA methyltransferase, plays a critical role in regulating tumor proliferation, migration, invasion, and progression." (PMID 41423530, 2025). "In vitro studies using colony formation and CCK-8 assays demonstrated that METTL3 knockdown inhibited cell proliferation, while overexpression of METTL3 through transfection with a pcDNA3.1-METTL3 plasmid promoted tumor proliferation." (PMID 39472692, 2025). "METTL3 expression was reduced in tumor-infiltrating NK cells, and METTL3 protein expression levels were positively correlated with NK cell effector molecules." (PMID 40529813, 2025). "Increasing evidence in recent years has shown that METTL3 participates in tumor cell proliferation, metastasis, and tumor microenvironment." (PMID 39980152, 2025). "Lacylation-driven METTL3-mediated RNA m6A modification plays an important role in promoting the immunosuppressive ability of tumor-infiltrating myeloid cells." (PMID 40495163, 2025). "Recent studies implicate numerous involvements of METTL3 in BC progression, comprising metastasis and tumor immune surveillance." (PMID 41157107, 2025). "Hua and colleagues showed that stable overexpression of METTL3 under in vitro experimental conditions significantly enhanced the ability of nude mouse cells to proliferate, form tumours, migrate, invade, and form tumours." (PMID 40356909, 2025). "Lactylation of METTL3 is essential for target RNA recognition and maintaining the immunosuppressive capacity of tumor-infiltrating myeloid cells." (PMID 40651967, 2025). "For example, in tumor cells, the m6A writers METTL3 and METTL14 suppress the expression of chemokines CXCL9 and CXCL10, leading to immune exclusion." (PMID 40176140, 2025). "After overexpression of METTL3, mice showed faster tumor growth (tumor volume increased by 96% and tumor weight increased by 2.12 times at 30 days), which was reversed by sh-BFSP1." (PMID 40097750, 2025). "Our findings suggest a tumor‐suppressive role for METTL3 in the early stages of HCC, emphasizing the importance of understanding the dynamic role of epigenetic regulation in tumorigenesis and targeted therapy." (PMID 40103332, 2025). "Mice with heterozygous loss of Mettl3 displayed intermediate phenotypes, underscoring a dose-dependent effect in cooperation with BRAFV600E to drive tumor progression." (PMID 39874138, 2025). "In vivo and clinical data supported the positive roles of the METTL3/SLC7A11 axis in tumor growth and progression." (PMID 39800682, 2025). "In vivo, METTL3 knockdown enhanced the efficacy of 5-FU and inhibited tumor metastasis, whereas STC2 overexpression counterbalanced these benefits." (PMID 40494964, 2025). "Evidence suggests that METTL14 and METTL3 have different implications for poor tumor prognosis in CRC." (PMID 39033180, 2024). "Collectively, these findings suggest that METTL3 controls the immunosuppressive tumour microenvironment in HPV‐induced CC, highlighting METTL3 as a potential therapeutic target for anti‐cancer immunotherapy." (PMID 38332508, 2024). "β-elemene extracted from the Chinese medicinal plant Curcuma Wenyujin is also shown to inhibit METTL3 activity and have tumor suppressive effects." (PMID 39600630, 2024).